HNF1A (HNF1 homeobox A)
Diseases named in the same sentence as HNF1A in open-access papers (continued):
Sharing a sentence is not in itself a finding about the gene and the disease.
MODY (continued). "These patients typically respond well to treatment with sulfonylurea, which increases insulin release from beta cells and is currently considered the treatment of choice for patients with HNF1A-MODY." (PMID 28593615, 2017). "It is well established that patients with HNF1A MODY are very sensitive to sulphonylureas (SU) and can be taken off insulin treatment after the proper molecular diagnosis." (PMID 26942212, 2016). "Three controls from the first control group (29.2%, 17.8%, and 14.3%) and two HNF1A-MODY patients (9.5% and 13.7%) were also characterized by high frequency of Akkermansia." (PMID 27807544, 2016). "The aim of our study was to test newly proposed clinical criteria for the identification of HNF1A MODY in patients with a diagnosis of T1DM or T2DM." (PMID 26942212, 2016). "The first control group, matched for age (p = 1.0) and BMI (p = 0.26) with HNF1A-MODY group, consisted of 16 healthy individuals (11 women and 5 men) with median age of 39.5 (31.5–49.5) years and median BMI of 23.77 (22.85–24.95) kg/m2." (PMID 27807544, 2016). "We obtained data of continuous glucose monitoring from 21 patients with T2DM and 9 patients with HNF1A-MODY." (PMID 27807544, 2016). "HNF1A-MODY is a clinically progressive phenotype with progressive hyperglycemia, glycosuria, and decreased renal function or microvascular complications, which can be reduced substantially by early treatment." (PMID 27142837, 2016). "HNF1A-MODY is a clinically progressive phenotype with hyperglycemia, glycosuria, and decreased renal function or microvascular complications, and usual associations with microvascular and macrovascular complications commensurate with glycemic control." (PMID 27142837, 2016). "We report in this study the successful generation of murine iPSCs from wild type and diabetic db/db animals, as well as reprogrammed human cells from control individuals and diabetic HNF1A MODY patients." (PMID 25716801, 2015). "Patients with GCK-MODY had higher IDL-C levels than control (p = 0.0002), T1DM (p = 0.0002) and HNF1A-MODY groups (p = 0.0044)." (PMID 24549415, 2014). "Among patients with GCK- or HNF1A-MODY, nine individuals in both groups showed considerable similarities of their lipid profile, suggesting the existence of a MODY-specific effect." (PMID 24549415, 2014). "Heterozygous mutations in the genes encoding the glycolytic enzyme glucokinase and the transcription factors, HNF-1α, HNF-4α and HNF1β have been shown to cause MODY." (PMID 24299156, 2014). "Levels of the large LDL subpopulation were lower in both GCK- and HNF1A-MODY groups than in controls (p = 0.0002 and 0.0002, respectively) and T1DM (p = 0.0002 and p = 0.0010, respectively)." (PMID 24549415, 2014). "To provide a molecular validation of these clinical findings, we turned to a cellular model of MODY where suppression of HNF1A or HNF4A function in INS-1 cells is achieved through the expression of DN-HNF1A or DN-HNF4A mutants." (PMID 23803251, 2013). "In contrast, hsCRP showed a specificity of 89% in identifying HNF1A-MODY patients, at reduced sensitivity (77%) though." (PMID 23803251, 2013). "ROC analysis on all data with the exclusion of the two patients with extreme hsCRP levels demonstrated that PSP/reg1A showed 90% sensitivity in identifying HNF1A-MODY patients, but with reduced specificity (67%)." (PMID 23803251, 2013). "The marker sCD36 warrants further investigation in a larger population of HNF1A-MODY carriers and control subjects." (PMID 24069322, 2013). "HNF1A and HNF4A mutations cause a similar clinical phenotype of MODY, characterized by progressive beta-cell dysfunction, defects in glucose-stimulated insulin secretion and sensitivity to low-dose sulphonylureas." (PMID 23803251, 2013). "Because the clinical course led to a probable diagnosis of MODY, we analyzed HNF1A, 4A and -1B by polymerase chain reaction and direct sequencing, according to a previous report." (PMID 22672869, 2012).
MODY (continued). "The researchers attributed the findings to the nature of the beta cell defect in MODY, as HNF1A is responsible for the expression of genes involved in glucose uptake, glycolysis, and mitochondrial metabolism." (PMID 22996131, 2012). "The most common MODY forms are caused by mutations in the glucokinase gene (GCK) and the hepatocyte transcription factor genes HNF1A and HNF4A." (PMID 22662265, 2012). "Therefore, the aim of the current study was to look for potential molecular alterations in the ECs related to HNF1A-MODY disease." (PMID 41749365, 2026). "Sulfonylureas, particularly in HNF1A-related MODY, are effective and may obviate the need for insulin." (PMID 40777711, 2025). "GCK, HNF4A and HNF1A are the most common types of MODY in China." (PMID 40303944, 2025). "Most often, MODY is caused by LOF variants in the coding regions of TF genes, but it can also be due to LOF variants in the cis-regulatory elements (CREs) of these genes, as has been shown, for example, for HNF1A and HNF4A." (PMID 41356216, 2025). "Mutations in HNF1A, PDX1, and HNF1B, which affect pancreatic development, have been associated with increased risk of monogenic forms of maturity onset diabetes of the young (MODY types 3, 4, and 5) and pancreatic cancer." (PMID 40427173, 2025). "Firstly, although the reported alleles are rare, destabilise the HNF1A protein, and are predicted to be pathogenic, they have not yet been associated with MODY onset cases." (PMID 40332430, 2025). "Specifically, mutations in the HNF1A, HNF4A, and GCK genes are known to cause MODY." (PMID 40869931, 2025). "Many cases of MIDY and MODY require insulin therapy, however, MODY 1 and MODY 3, caused by mutations in the transcription factors hepatocyte nuclear factor 4α (HNF4A) and 1α (HNF1A), respectively, can often improve insulin secretion with sulfonylurea treatment." (PMID 40666490, 2025). "As GCK, HNF1A, and HNF4A variants make up almost 80% of all MODY cases, it may be prudent to test for these first." (PMID 39717432, 2025). "In many MODY-associated TF genes, homozygous LOF variants are generally thought to be embryonically lethal or result in early mortality, e.g., in GATA4, GATA6, HNF1A, HNF1B, HNF4A, and ONECUT1." (PMID 41356216, 2025). "Among the HNF1A-MODY patients, both were obese at the time of diagnosis." (PMID 41367630, 2025). "The sulfonylurea trial was empiric, based on the clinical presentation, history, and laboratory results, as genetic subtype confirmation of MODY (e.g., HNF1A or HNF4A mutations) was not available." (PMID 41306149, 2025). "For example, some MODY patients may retain sufficient endogenous insulin secretion to avoid transplantation altogether, or may respond to oral hypoglycemic agents, particularly sulfonylureas, in HNF1A-MODY." (PMID 40869931, 2025). "Similarly, in Norway, HNF1A accounted for 53% of MODY cases, GCK for 30%, HNF4A for 7.5%, and HNF1B for 5.6%." (PMID 41153735, 2025). "Moreover, the accumulation of data on genetically confirmed MODY associated with the coinheritance of GCK and HNF1A variants will be useful for understanding genotype–phenotype correlations." (PMID 39089324, 2024). "The molecular endocrinological mechanisms of MODY associated with coinheritance are complex and may be explained by the following mechanisms: (i) GCK and HNF1A exist in the same pathway in beta-cell function." (PMID 39089324, 2024). "Therefore, regular screening for retinopathy and nephropathy in individuals with MODY, especially with variants in HNF4A, HNF1A, and HNF1B, is recommended." (PMID 39511990, 2024). "However, mutations in HNF1A, GCK, and HNF4A are the most common causes of MODY, accounting collectively for 85–90% of all cases." (PMID 39408828, 2024). "Careful clinical follow-up is needed to determine the phenotype, especially in pediatric patients, of the coinheritance of MODY involving GCK and HNF1A variants, which may reflect having some combined effect on glucose metabolism." (PMID 39089324, 2024).
MODY (continued). "When there is a family history suggestive of maturity-onset diabetes of the young (MODY), genetic testing for HNF1A and HNF4A should be considered because these conditions can cause transient hyperinsulinism in the newborn period." (PMID 37454648, 2024). "In our cohort, the prevalence of pathogenic variants on these genes were respectively, 0.006%, 0.080%, and 0.006%, which demonstrated a higher prevalence for GCK-MODY, and lower for HNF1A-MODY and HNF4A-MODY comparing to other cohorts, including UK biobank and Geisinger cohort." (PMID 39191897, 2024). "Herein, we report a case of MODY with coinheritance of monoallelic variants in GCK and HNF1A." (PMID 39089324, 2024). "Outside of pregnancy, HNF1A-MODY is optimally managed with low dose SU therapy." (PMID 38933924, 2024). "Unlike shown in previous studies that variations in HNF1A were the most common cause of MODY in Europe, North America, and Asia, it was not the most frequent cause in our study, which identified three pathogenic variants." (PMID 37327085, 2023). "Mutations in GCK, HNF1A, HNF1B, and HNF4A account for approximately 80% of the MODY cases." (PMID 37941991, 2023). "Lower values were found in patients with HNF1A-MODY, with an area under the ROC curve of 0.91." (PMID 36747290, 2023). "Until now, scientific interest was mostly focused on HNF1A-related MODY and GCK-related MODY." (PMID 37511676, 2023). "The genetic alterations of glucose metabolism, such as glucose-6-phosphatase, catalytic (G6PC), maturity-onset diabetes of the young type 3 (MODY3) and hepatocyte nuclear factor-1 alpha (HNF1A) genes, lead to glycogen storage diseases." (PMID 37622118, 2023). "The treatment of HNF1A-MODY patients depends on their age and HbA1c level." (PMID 35299962, 2022). "Finally, the sample size of the HNF1A-MODY group was relatively small, which was dependent on the specific MODY subtypes prevalent in China." (PMID 36387841, 2022). "For instance, we might accept a high cost per detected mutation when a positive result may lead to a more tailored treatment approach, such as HNF1A‐MODY, which can be efficiently managed with sulphonylureas instead of insulin." (PMID 35822264, 2022). "Identification of other genetic factors influencing the age of HNF1A-MODY presentation could provide numerous clinical benefits." (PMID 36104811, 2022). "HNF1A-MODY is typically diagnosed in the second or third decade of life." (PMID 36104811, 2022). "In this review, we discuss the similarities and differences in the pathophysiological role of HNF1A in patients with MODY and T2DM, however, few reports were found directly comparing the effects of HNF1A mutations in MODY3 and T2DM-related HNF1A common variants." (PMID 35328643, 2022). "In a recent study, among 16 patients with MODY who were offered treatment switch after genetic diagnosis, nine (six HNF1A, three KCNJ11) were stably switched from insulin to oral sulfonylurea but seven (three HNF4A, two ABCC8 and one each HNF1A and KCNJ11) had to restart insulin." (PMID 35618782, 2022). "Mutations in GCK, HNF1A and HNF4A are the most common causes of MODY." (PMID 34789499, 2022). "Mutations in the hepatocyte nuclear factor 1-alpha (HNF1A), glucokinase (GCK), hepatocyte nuclear factor 4-alpha (HNF4A), and hepatocyte nuclear factor 1-beta (HNF1B) genes are the most frequently identified aetiologies of MODY." (PMID 34496959, 2021). "Among them, mutations in HNF4A, HNF1A, and GCK are the most common causes of MODY." (PMID 33663443, 2021). "The most common transcription factors that cause MODY when mutated belong to the hepatocyte nuclear factor (HNF) family (HNF4A, HNF1A and HNF1B), resulting in MODY1, MODY3 and MODY5, respectively, but other causal transcription factor genes have also been described." (PMID 34440499, 2021).
MODY (continued). "In particular, HNF1A maturity-onset diabetes of the young (MODY) is very amenable to therapy with sulfonylureas, whereas, for GCK MODY, no pharmacological treatment is recommended, and diet and regular physical activity are necessary to maintain good glycemic control." (PMID 33810109, 2021). "Moreover, mutations in GCK, HNF1A, and HNF4A HNF1B are the most common causes of MODY, accounting for 32%, 52%, 10% and 6% of all infected patients in the UK, respectively." (PMID 34421822, 2021). "HNF1A-MODY, also known as MODY-3, is more frequent in the United Kingdom and the Netherlands." (PMID 34496959, 2021). "Additionally, we reviewed the literature concerning the phenotypes of MODY 3 and HCA at the background of HNF1A mutations." (PMID 31754975, 2020). "The mutations of HNF1A (MODY3) and GCK (MODY2) accounted for 9% and 1% of MODY cases in China, respectively, and a majority of Chinese pathogenic gene of MODY is unknown." (PMID 32411229, 2020). "When used to compare HNF1A with other MODY types, a 0.55 mg/L cutoff point may be useful to decide priority of sequencing in the context of using Sanger sequencing and testing genes separately." (PMID 32528556, 2020). "In summary, our study enabled us to evaluate the cosegregation of HCA and MODY 3 with loss of function mutations of HNF1A, and advised systematic screening of HCA through noninvasive liver imaging in MODY 3 pedigrees." (PMID 31754975, 2020). "Microvascular complications, particularly retinopathy, seem to be common in HNF1A-MODY patients." (PMID 31739614, 2019). "Out of fourteen, up to date discovered, MODY genes the most often affected ones include GCK (gene encoding glucokinase enzyme) and HNF1A (encoding the transcription factor—hepatocyte nuclear factor 1α), which altogether account for approximately 80% of all MODY cases." (PMID 30013516, 2018). "Establishing a genetic diagnosis of HNF1A-MODY may lead to treatment changes for previously misdiagnosed patients, even to the discontinuation of assumed life-long insulin treatment." (PMID 29666556, 2018). "Our findings showed HNF1A and ABCC8 to be the most frequently mutated MODY genes in south India." (PMID 29439679, 2018). "Interestingly, in this study population, utilizing the NGS we have identified MODY variants in NEUROD1, PDX1 and BLK genes in comparison to the more commonly reported HNF4A, GCK and HNF1A gene variants." (PMID 28095440, 2017). "To analyze the frequencies of the carriers of such mutations in our cohort, we analyzed genes (HNF1A, HNF4A, HNF1B, INS, ABCC8, and KCNJ11) in which a significant number of missense mutations have previously been reported in MODY, neonatal diabetes mellitus, or early onset diabetes." (PMID 29207974, 2017). "Similarly, several MODY-associated genes, including GCK, HNF1A and HNF1B, are important for maintaining normal hepatic function." (PMID 27185732, 2016). "HNF1A-MODY (MODY3) is the most common form of the disorder in white populations and is caused by mutations and, rarely, deletions affecting HNF-1α, a transcription factor that functions in the transcriptional network necessary for liver as well as pancreatic β-cell development and function." (PMID 27142837, 2016). "After case reports of sulphonylurea sensitivity in this patient group, a randomized crossover trial of sulphonylureas and metformin in patients with HNF1A MODY and patients with Type 2 diabetes established that patients with this subtype of MODY are exquisitely sensitive to sulphonylurea treatment." (PMID 26802434, 2016). "HNF1A-MODY is one of the most common forms of subtypes of MODY." (PMID 27807544, 2016). "GCK‐ and HNF1A‐MODY each account for approximately 20–50% of all MODY cases." (PMID 26059258, 2016). "So far, the ghrelin level in human HNF1A gene mutation carriers or other MODY subjects has not been examined, while data from type 1 (T1DM) and type 2 diabetes (T2DM) are limited." (PMID 25987348, 2015).
MODY (continued). "MODY shows extreme allelic heterogeneity meaning that most MODY mutations are unique; to date, there are more than 200 mutations described in the GCK (MODY2) and HNF1A (MODY3) genes." (PMID 25774817, 2015). "Currently, mutations in the HNF1a gene are known to be the most common cause of maturity onset diabetes of the young (MODY), a severe dominantly inherited form of nonketotic diabetes mellitus that is characterized by pancreatic beta-cell dysfunction." (PMID 25057215, 2014). "We have provided preliminary clinical proof-of-concept, and have mechanistically validated that the parallel measurements of serum PSP/reg1A and hsCRP levels in subjects with clinically suspected MODY may discriminate HNF1A-MODY from HNF4A-MODY." (PMID 23803251, 2013). "Testing for HNF4A mutations is recommended when HNF1A genetic analysis does not show a mutation in individuals with clinical features of MODY or in diabetic family members with macrosomia or diazoxide-responsive neonatal hyperinsulinism." (PMID 23803251, 2013). "HNF1A MODY patients showed much a better response to gliclazide than the patients with T2DM and this difference was associated with a great insulin secretion improvement in MODY patients." (PMID 22996131, 2012). "MODY are also associated with mutations in the genes encoding transcription factors like, hepatic nuclear factor 4 alpha (HNF4A), HNF1 homeobox A (HNF1A), pancreatic and duodenal homeobox 1 (PDX1), HNF1 homeobox B (HNF1B) and neurogenic differentiation 1 (NEUROD1)." (PMID 22399922, 2010). "Moreover, for HNF1A and HNF4A, disruption of positive feedback and of cooperativity has been identified as the cause of MODY." (PMID 41356216, 2025). "We presented herein a robust sample of 100 patients with confirmed variants in the GCK gene, 202 patients with clinical characteristics of MODY but no variants in either GCK or HNF1A, and 2,687 patients with T1D, obtained from data leveraged from two Brazilian multicenter cohorts." (PMID 39420902, 2024). "Specifically, in MODY 3, individuals with the HNF1A mutation may present with normal plasma glucose levels and only glycosuria." (PMID 39055415, 2024). "In people with MODY due to HNF4A mutations, early life hypoglycaemia due to insulin hypersecretion is also described, and may be sustained, while 7% of those deficient for HNF1A develop liver adenomatosis." (PMID 35618782, 2022). "However, the clinical symptoms of HNF1A-MODY are very different." (PMID 35299962, 2022). "Although the GCK (MODY 2), HNF1A (MODY 3), and HNF4A (MODY 1) genes are responsible for the vast majority of genetic causes of MODY, there are other rarer MODY subtypes caused by mutations in genes not analyzed in this study, which could have been analyzed by next-generation sequencing methods." (PMID 31968686, 2020). "Therefore, clinicians may consider treating patients who have HNF1A-MODY with GLP-1 RAs, especially if episodes of hypoglycemia limit the tolerability of sulfonylureas." (PMID 33292863, 2020). "It is possible that patients without HNF1A mutations could have alterations in other MODY genes, which would be overlooked with this strategy." (PMID 31576961, 2020). "Patients with MODY (maturity onset diabetes of the young), which is caused by mutations in an autosomal dominant gene, are known to show distinct phenotypes between the HNF1B (MODY5) and HNF1A (MODY3) mutations due to differences in the expression level and the time and site of their expression." (PMID 27196561, 2016).